HIF1A (hypoxia inducible factor 1 subunit alpha)
Diseases named in the same sentence as HIF1A in open-access papers (continued):
Sharing a sentence is not in itself a finding about the gene and the disease.
medulloblastoma (14 papers, 2012 to 2024). A malignant, invasive embryonal neoplasm arising from the cerebellum. "Human SHH-medulloblastoma tumors with higher REST expression exhibit nuclear localization of HIF1α, in contrast to its cytoplasmic localization in low-REST tumors." (PMID 38866867, 2024). "HIF1α promoted drug resistance in human medulloblastoma by inhibition of CYP2B6, CYP3A4 and CYP3A5 expression, which in turn resulted in decreased conversion of CPA and IFA into their active forms and thus to diminished cytotoxicity." (PMID 35355718, 2022). "Combination of VEGFA and HIF-1α inhibitors could provide a synergistic combination therapy against medulloblastoma." (PMID 37568705, 2023). "In 82.3 cells, we observed overexpression of HIF1A; in medulloblastoma, the upregulation of HIF1A correlated with a worse response to cyclophosphamide through the inhibition of a gene of the cytochrome p450 family, CYP3A5, also found to be down-regulated in our model." (PMID 33922695, 2021). "In addition to VEGFA, emerging evidence suggests that hypoxia-inducible factor 1 alpha (HIF-1α) may also play a critical role in medulloblastoma pathogenesis." (PMID 37568705, 2023). "The presence of hypoxia has been shown to upregulate hypoxia-induced factor (HIF1-α), but this alters the CYP isoforms differently in various medulloblastoma cell lines." (PMID 34262860, 2021). "Transactivated by HIF-1α, MYC is a prominent biological determinant in SHH (MYCN) and group 3 (MYCC) medulloblastoma but has not been widely implicated in group 4 biology, although MYCN amplifications are infrequently observed." (PMID 29880060, 2018). "In the early exploration of medulloblastoma, it was recognized that hypoxia-induced hypoxia-inducible factor (HIF)-1α could sustain Neurogenic locus notch homolog protein 1 (Notch 1) in its active form by preserving medulloblastoma CSC viability and expansion." (PMID 37370764, 2023).
Granuloma (13 papers, 2012 to 2025). A compact, organized collection of mature mononuclear phagocytes, which may be but is not necessarily accompanied by accessory features such as necrosis. "Furthermore, suppression of granuloma-associated angiogenesis – which would be expected to cause hypoxia and induce the expression of HIF-1α – decreased M. marinum burden." (PMID 39717773, 2024). "Inhibition of HIF‐1α in these anti‐IL‐17 mice improved infection outcome, reducing granuloma size and reversing excess inflammation." (PMID 32633061, 2020). "Together these recent data show critical roles of HIF‐1α in both innate immune cell TB control and in later stage granuloma pathogenesis." (PMID 32633061, 2020). "In situ hybridization of sarcoidosis granulomatous lung tissues showed abundance of HIF-1α in the center of granulomas." (PMID 30946009, 2019). "The pathogen induces formation of granulomas, which become hypoxic, leading to stabilization of hypoxia-inducible factor 1α (HIF-1α)." (PMID 31036602, 2019). "Positive immunostaining was seen in multinucleated giant cells of granulomas as well as macrophages (thick arrow), whereas fibroblasts and normal lungs lack HIF-1α expression." (PMID 30946009, 2019). "Since H. capsulatum-induced granulomas in mice represent a hypoxic environment in which HIF-1α expression is enhanced in macrophages, we asked if HIF-1α is stabilized in MDM upon H. capsulatum infection in normoxia or hypoxia." (PMID 31036602, 2019). "Epithelioid macrophages and Langerhans giant cells were immunoreactive for HIF-1α staining within TB granulomas compared with uninfected control lung tissue, demonstrating that TB infection causes HIF-1α accumulation." (PMID 27245780, 2016). "To investigate the relevance of HIF-1α to TB granulomas in patients, we performed immunohistochemical analysis of lung biopsy specimens from patients with a confirmed diagnosis of TB." (PMID 27245780, 2016). "For example, Hif-1α mediated TNF activation may be pertinent in later TB infection situations where granulomas have stabilized Hif-1α due to necrotic and hypoxic centers." (PMID 31611882, 2019). "Reduced activity of HIF-1a due to ING4 overexpression may promote an angiostatic environment within granulomas, while VEGF could be responsible for macrophage chemotaxis." (PMID 23181555, 2012). "In vitro findings are supported by immunohistochemistry data, demonstrating the expression of HIF-1a and its target PAI-1 in epithelioid cells forming pulmonary sarcoidosis granulomas." (PMID 38611622, 2024). "These in vitro results were supported by immunohistochemistry data showing the expression of HIF-1α and its target PAI-1 in epithelioid cells constituting pulmonary sarcoidosis granulomas." (PMID 34456926, 2021). "Nuclear localization of HIF-1α and PAI-1 was detected in the mature epithelioid cells constituting granulomas." (PMID 34456926, 2021). "Our data suggest an impairment of the HIF-1a – VEGF axis, potentialy arising by ING4 overexpression and ultimately resulting in angiostasis and monocyte recruitment within granulomas." (PMID 23181555, 2012). "HIF-1a promotes angiogenesis through the transcription of various mediators, including VEGF which was found to be abundantly expressed inside granulomas." (PMID 23181555, 2012). "Hypoxia-induced HIF-1α also induces expression of CXCR4 – the receptor for the lymphocyte chemokine (and pro-angiogenic) CXCL12; thus, HIF-1α maintains both the influx of potentially host-protective immune cells to granulomas and the viability of these cells." (PMID 39717773, 2024). "We immunodetected HIF-1α and PAI-1 in granulomas from the three archived pulmonary biopsies." (PMID 34456926, 2021).
influenza (13 papers, 2017 to 2025). An acute viral infection of the respiratory tract, occurring in isolated cases, in epidemics, or in pandemics; it is caused by serologically different strains of viruses (influenzaviruses) designated A, B, and C, has a 3-day incubation period, and usually lasts for 3 to 10 days. "Mice treated intratracheally with HIF-1α activator (FG-4592) experienced reduced TR-AM loss, airway inflammation, and improved survival in a lethal model for influenza-induced ARDS." (PMID 40092977, 2025). "For the target search, we applied a PPI network to identify the top three hub genes associated with influenza (IL-6, HIF1A, and IL-1β)." (PMID 39000173, 2024). "Next, PPI network analysis identified the top three hub genes associated with influenza (IL-6, HIF1A, and IL-1β)." (PMID 39000173, 2024). "Influenza A virus (H1N1) infection causes induction of hypoxia response by stabilizing HIF1α." (PMID 39601573, 2025). "From our PPI analysis, we identified HIF1A as one of the key targets associated with influenza." (PMID 39000173, 2024). "Moreover, HIF1a is known to be causally involved in the reaction to inflammatory lung contusion and is extensively associated with immune cell function, and with reaction to influenza and tuberculosis infections." (PMID 33163005, 2020). "In contrast, Zhu and colleagues have shown that in vitro treatment with Poly (I:C), a synthetic viral immunostimulant, or influenza infection induces HIF-1α in TR-AMs, but we were unable to reproduce these results." (PMID 40092977, 2025). "On the other hand, a knockdown of HIF-1α in a human epithelial cell line has been shown to promote influenza replication." (PMID 39203555, 2024). "To determine how the ability to adapt to hypoxia affects TR-AM survival and function, we treated influenza-infected mice intratracheally with FG-4592, a HIF-1α stabilizer, which mimics hypoxic adaptation." (PMID 35822617, 2022). "Third, through network pharmacology and molecular docking analysis, the TLR4/NF-κB p65 signaling pathway and HIF-1α/IL17 signaling pathway were found to be highly related to the anti-inflammatory action of HSSD in treating influenza." (PMID 36386710, 2022). "Recent studies have highlighted the important role of hypoxia-inducible factor 1-alpha (HIF-1α) in influenza-induced immune modulation, regulation of inflammatory responses, and virus pathogenesis, proposing it as a potential target for strategic intervention in influenza infection." (PMID 41511331, 2025). "Recent research reported that influenza infection induced the nuclear translocation of HIF1A, which may promote the production of proinflammatory cytokines." (PMID 39000173, 2024). "Furthermore, when mice were treated with a HIF-1α stabilizer at the time of influenza infection, TR-AM survival was increased and accompanied by reduced lung injury and death." (PMID 35822617, 2022). "Interestingly HIF-1α-knockout macrophages show decreased expression of iNOS after IFNγ stimulation, indicating the possible involvement of HIF-1α in influenza pathogenesis." (PMID 32161622, 2020). "Huoxiang Suling Shuanghua Decoction exerts an anti-influenza effect by affecting the expressions of mRNA and protein including TLR4, CD14, MyD88, NF-kB p65, HIF-1α, VEGF, IL17A, IL6, and inhibiting the accumulation of inflammation." (PMID 36386710, 2022). "Overall, our results suggest that HSSD exerts pharmacological activity against influenza through multiple targets involved in TLR4/NF-κB p65 signaling pathway and the HIF-1α/IL17 signaling pathway." (PMID 36386710, 2022). "Next, eight key targets were identified, including TLR4, CD14, MyD88, NF-κB p65, HIF1 α, VEGF, IL17A, and IL6, which were verified to be key targets for HSSD in the treatment of influenza." (PMID 36386710, 2022). "We have shown that HIF-1α is not required for steady-state function or for proinflammatory processes in TR-AMs, but is critical in promoting TR-AM survival during influenza-induced ARDS in mice." (PMID 40092977, 2025).
influenza (continued). "In agreement with our findings, Zhu and colleagues recently showed that TR-AMs at D6 of influenza infection have high HIF-1α expression; however, they suggested that HIF-1α stabilization in TR-AMs worsens lung injury through enhanced proinflammatory effector function." (PMID 35822617, 2022). "This indicates that the role of HIF-1α has not been completely established in influenza infections." (PMID 39203555, 2024). "Thus, the TLR4, CD14, MyD88, and NF-κB p65 in TLR4/NF-κB p65 signaling pathway, HIF1 α, VEGF, IL17A, and IL6 in HIF-1α/IL17 signaling pathway may be the targets responsible for the anti-inflammatory function of HSSD in treating influenza." (PMID 36386710, 2022). "In conclusion, our study suggested that TLR4, CD14, MyD88, NF-κB p65, HIF1 α, VEGF, IL17A, and IL6 in the TLR4/NF-κB p65 signaling pathway and HIF-1α/IL17 signaling pathway may be the key targets for the identified active compounds of HSSD to treat influenza by inhibiting inflammatory responses." (PMID 36386710, 2022).
lupus (13 papers, 2015 to 2026). "Firstly, limited studies discussed polymorphisms in the HIF-1α gene and lupus, IBD." (PMID 36761171, 2022). "pointed out that renal hypoxia contributes to heightened T cell infiltration and kidney damage, partially mediated by HIF-1α-induced metabolic reprogramming in lupus-prone mice (MRL/lpr mice)." (PMID 39575238, 2024). "mTOR and HIF-1α play a critical role in regulating cell growth and proliferation (e.g., Th17 cells), which are related to the abnormal development of T cells in lupus mice and SLE patients." (PMID 34434237, 2021). "The present study addresses the role of two additional transcription factors, liver X receptor-alpha (LXRα) and hypoxia inducible factor 1-alpha (HIF1α), in lupus." (PMID 29456535, 2018). "Although CD138+ Mφ from lupus (pristane-treated) mice were more “inflammatory” than those from MO-treated controls, Hif1a expression was still higher in peritoneal M1-like Ly6Chi than in M2-like CD138+ Mφ from pristane-treated mice." (PMID 29456535, 2018). "The altered expression of LXRα and HIF-1α in mice with pristane-lupus prompted us to look for similar changes in circulating monocytes from SLE patients." (PMID 29456535, 2018). "We show that an imbalance between LXRα and HIF1α activity is involved in the pathogenesis of end-organ damage (DAH) in lupus." (PMID 29456535, 2018). "Overexpression of HIF-1α has been detected in human lupus CD4+ T cell subsets, indicating that abnormal expression of HIF-1α may be involved in the immune dysregulation of SLE (Garchow, Maque Acosta & Kiriakidou, 2021)." (PMID 40585331, 2025). "Some lupus patients had increased expression of HIF1A by GSVA." (PMID 34285256, 2021). "Our data suggested that HIF1α inhibitors or LXR agonists might benefit lupus patients by promoting M2 Mφ polarization." (PMID 29456535, 2018). "BOLD-MRI showed that the reduced R2* values in the renal cortex and medulla of lupus mice were increased when treated with anti-P-selectin mAb as compared with those treated with normal saline, which were negatively correlated with HypoxyprobeTM-1 hypoxia probe and the expression of HIF-1α." (PMID 32138730, 2020). "HIF1α has been reported to be upregulated in the kidneys of LN patients and in peripheral CD4+ T cells of lupus patients; however, the mechanisms behind the abnormal levels of HIF1α are still unclear." (PMID 40728997, 2025). "HIF-1α is also involved in the pathogenesis of systemic lupus erythematosus (SLE)." (PMID 35684364, 2022). "Thus, HIF-1α may be a promising target for treatment of lupus." (PMID 36761171, 2022). "Similarly, lupus patients’ monocytes exhibited low LXRα/ABCA1 and high HIF1α vs. controls." (PMID 29456535, 2018).
von Hippel-Lindau disease (13 papers, 2008 to 2024). An autosomal dominant disorder caused by pathogenic variants in the VHL gene, leading to an increased risk of various benign and malignant tumors, including hemangioblastomas, retinal hemangiomas, endolymphatic sac tumors, renal cell carcinoma, and pheochromocytomas. "The Von Hippel-Lindau (VHL) syndrome has been rarely associated with renal oncocytomas, and tumors usually show HIF1α chronic stabilization." (PMID 30728892, 2019). "Emphasizing HIF importance for regulating cell outcomes such as enhanced proliferation, patients with Von Hippel Lindau disease (pVHL) who lack the protein mediating HIF1α degradation, are predisposed to develop a range of highly vascularized tumors." (PMID 29257069, 2017). "Many tumor types, such as RCC, and those tumors associated with von-Hippel Lindau (VHL) syndrome create “pseudohypoxia” via inactivating mutations of the VHL protein that would normally ubiquitinate HIF-1α." (PMID 26934654, 2016). "RCC and other tumors in von Hippel-Lindau syndrome patients are outliers in that disease progression is often associated with loss of HIF-1α expression, which may be due in part to selection against HIF-1α–dependent inhibition of MYC activity." (PMID 35642641, 2022). "In patients with von Hippel–Lindau syndrome, the tumor suppressor gene is mutated and pVHL is absent, limiting HIF1α degradation." (PMID 38279330, 2024). "However, under normoxia the polyubiquitylation of HIF-1α by Von Hippel-Lindau syndrome (VHL) degraded HIF-1α in proteasome." (PMID 28165392, 2017).
alcoholic liver diseases (12 papers, 2015 to 2025). A disorder caused by damage to the liver parenchyma due to alcohol consumption. "The regulation of intestinal microbial homeostasis by the HIF1α-AMP axis has been implicated previously in the context of alcoholic liver disease." (PMID 31372513, 2019). "Interestingly, in human alcoholic liver disease, HIF-1α has also been associated with both hepatoprotective effects, as well as reduced dysbiosis, and an increased intestinal barrier." (PMID 38338821, 2024). "Up-regulated HIF1α and HIF2α increase hepatic inflammation, and contribute to alcoholic or non-alcoholic liver disease and acetaminophen induced liver injury." (PMID 29311569, 2018). "We also quantified the activity of HIF-1α, one of the major regulators of oxidative stress generation in alcoholic liver diseases." (PMID 25722794, 2015). "Interestingly, ethanol induced HIF-1α signaling is recognized as a mediator of Alcoholic Liver Disease." (PMID 29045486, 2017). "Increased expression of both HIF-1α and HIF-2α has been observed in several chronic liver diseases, including alcoholic liver disease (ALD), NAFLD and HCC." (PMID 33400730, 2020).